MRPS23 (mitochondrial ribosomal protein S23)
Diseases named in the same sentence as MRPS23 in open-access papers (continued):
Sharing a sentence is not in itself a finding about the gene and the disease.
glioma (4 papers, 2024 to 2026). A benign or malignant brain and spinal cord tumor that arises from glial cells (astrocytes, oligodendrocytes, ependymal cells). "MRPS23 expression associated with clinical pathological characteristics in glioma (logistic regression)." (PMID 38301044, 2024). "Cox regression analyses showed that WHO grade and MRPS23 expression level were associated with glioma prognosis." (PMID 38301044, 2024). "We used CGGA database analysis and found that high expression of MRPS23 was associated with adverse clinical characteristics and poor prognosis in glioma patients." (PMID 38301044, 2024). "MRPS23 has been identified as a novel prognostic biomarker in glioma, adrenal cortical carcinoma, and colorectal cancer." (PMID 41522354, 2026). "MRPS23 exhibits oncogenic functions in glioma patients, promoting the cell proliferation and metastasis of glioma cells, and serves as an independent prognostic indicator." (PMID 39859078, 2025). "Mitochondrial ribosomal protein S23 (MRPS23) is elevated in diverse human cancers, promotes several malignant properties in glioma and contributes to the proliferation of hepatocellular carcinoma and breast cancer." (PMID 40102573, 2025). "In short, MRPS23 is not only a potential prognosis biomarker in cancer, but also a promising therapeutic target for glioma." (PMID 38301044, 2024). "We found that compared with normal astrocytes (NHA), MRPS23 was upregulated in glioma cell lines and glioma tissues." (PMID 38301044, 2024). "Univariate and multivariate Cox analysis demonstrated MRPS23 expression was independently prognostic of overall survival, disease-free survival, and progression-free survival in patients with glioma." (PMID 38301044, 2024). "First, we excavated TIMER database to examine the MRPS23 expression level in pan-cancers, indicating that MRPS23 was increased in diverse human cancer, especially in gliomas." (PMID 38301044, 2024). "To analyze GO and KEGG enrichment, we discovered the top 50 similar genes related to MRPS23 in glioma using the GEPIA database." (PMID 38301044, 2024). "Collectively, these findings offer mechanistic insights into how MRPS23 during glioma progression, and identify MRPS23 as a potential therapeutic target in the future." (PMID 38301044, 2024). "Higher expression of MRPS23 in gliomas correlated with poorer prognosis, unfavorable histological features, absence of mutations in the isocitrate dehydrogenase gene (IDH), absence of chromosome 1p and 19q deletions, and responses to chemoradiotherapy." (PMID 38301044, 2024). "MRPS23 can be used as a molecular predictor of cancer patients, and can be used as a clinical diagnosis and treatment target of glioma." (PMID 38301044, 2024). "Up-regulated MRPS23 had a worse OS in of glioma subgroups, including gender, IDH status (WT), 1p/19q codeletion (non-codel), histological type (astrocytoma), age (<=60), race (white)." (PMID 38301044, 2024). "Next, we combined the TCGA and GTEx cancer database, and found that MRPS23 was up-regulated in glioma than in paired adjacent normal tissues." (PMID 38301044, 2024). "In this study, we found that MRPS23 expression was higher in gliomas than in adjacent normal tissues." (PMID 38301044, 2024). "We also confirmed that MRPS23 was highly expressed in glioma cells lines, and MRPS23 knockdown significantly reduced cell survival, proliferation, and migration of glioma cells lines." (PMID 38301044, 2024). "Furthermore, MRPS23 also contributes to the malignant phenotypes of other types of cancer, including glioma, HCC, and cervical cancer." (PMID 39859078, 2025). "The migration ability of glioma cells was significantly inhibited after MRPS23 gene knockdown." (PMID 38301044, 2024). "Secondly, the molecular mechanism of MRPS23 upregulation in glioma remains unstudied." (PMID 38301044, 2024). "This study broadens our horizon of MRPS23 in glioma, but there are still some inconsistencies." (PMID 38301044, 2024).
glioma (continued). "The biological function of MRPS23 in glioma progression has been further explored and verified." (PMID 38301044, 2024). "We found that increased MRPS23 expression correlated with poor OS for glioma, HNSC, KICH, LAML, LIHC, and oral squamous cell carcinoma (OSCC), poor DSS in glioma, HNSC, KICH, KIRP, and OSCC, and poor PFI in adrenocortical carcinoma (ACC), glioma, HNSC, KICH, KIRP, LIHC, and OSCC." (PMID 38301044, 2024). "A nomogram was contrasted to confirm MRPS23 as a glioma biomarker to predict OS, DSS, and PFI." (PMID 38301044, 2024). "These confirmed that MRPS23 has an important role in glioma progression." (PMID 38301044, 2024). "The relationship between MRPS23 expression level and glioma pathology was also explored." (PMID 38301044, 2024). "In summary, MRPS23 plays a crucial role in regulating glioma malignant progression." (PMID 38301044, 2024). "However, little is known about the function of MRPS23 in glioma." (PMID 38301044, 2024). "In addition, our result indicated high MRPS23 expression correlated with poor OS for glioma, HNSC, KICH, LIHC, OSCC, and THCA, poor DSS in glioma, HNSC, KICH, KIRP, OSCC, and OV, and poor PFI in ACC, glioma, HNSC, KICH, KIRP, LIHC, and OSCC." (PMID 38301044, 2024). "MRPS23 had positive relationship with MSI in CESC, STES, SARC, KIRP, UCEC, and KIRC, and had negative relationship with glioma, LUAD, COAD, COADREAD, PRAD, LUSC, and OV." (PMID 38301044, 2024).
hepatocellular carcinoma (4 papers, 2020 to 2025). A malignant tumor that arises from hepatocytes. "However, MRPS23 overexpression was found to promote hepatocellular carcinoma cell proliferation and suggested a low survival rate in hepatocellular carcinoma patients." (PMID 33238645, 2020).
hepatic disease (2 papers, 2016 to 2021). "mS23 (MRPS23)—The mutation c.119C > G (p.Pro40Arg) in mS23 was identified in a single patient presenting with hepatic disease, with fibroblasts displaying decreased OxPhos complex I and IV enzymatic activity and reduced 12S rRNA abundance." (PMID 33917098, 2021). "A component of the highly conserved mitochondrial ribosome small subunit MRPS23 was mutated in Pt276, a boy with hepatic disease and combined respiratory chain complex deficiencies." (PMID 26741492, 2016).
lymph node metastases (2 papers, 2020 to 2026). "In total, 144 cases were examined for MRPS23 copy number status in their lymph node metastases." (PMID 31950385, 2020).
atherosclerosis (1 paper, 2025). A disease characterized by the build-up of fatty material and calcium deposition in the arterial wall resulting in partial or complete occlusion of the arterial lumen. "Expression of overlapping genes and FRGs (MRPS23, CASP8) were verified using qRT-PCR in normal, Atherosclerosis and Atrial Fibrillation patients." (PMID 40607061, 2025).
B-cell neoplasm (1 paper, 2024). A group of heterogeneous lymphoid tumors generally expressing one or more B-cell antigens or representing malignant transformations of B-lymphocytes. "Additionally, our team ensured the relationship between MRPS23 and mutation, alteration frequencies were 5.26%, 4.6%, 3.02%, and 2.19% in BRCA, pleural mesothelioma, endometrial cancer, BLCA, HNSC, and mature B-Cell neoplasms." (PMID 38301044, 2024).
deficiencies (1 paper, 2016). "We newly confirmed 3 mitochondria-related genes (MRPS23, QRSL1, and PNPLA4) as causative genes of mitochondrial respiratory chain complex deficiencies." (PMID 26741492, 2016). "We ultimately identified 41 mutations, of which 37 were novel, in 20 genes that were previously reported to cause OXPHOS disease and 3 novel mitochondria-related genes (MRPS23, QRSL1, and PNPLA4) as causative genes of mitochondrial respiratory chain complex deficiencies." (PMID 26741492, 2016).
heart attack (1 paper, 2025). "Additionally, MRPS23 and HMGN1 contribute to mitochondrial dysfunction and stress response regulation, exacerbating cell damage and inflammation, ultimately promoting heart attack (myocardial infarction) through increased ROS and DNA damage." (PMID 40775796, 2025).
Hypoglycemia (1 paper, 2023). A decreased concentration of glucose in the blood. "This study highlights the specific MRPS23 variant associated with lactic acidosis and hypoglycemia, which has significant implications for individuals of Hmong ancestry carrying the homozygous c.119C>T; p.P40L variant." (PMID 38086984, 2023). "Given the high prevalence of this variant, it is crucial to prioritize MRPS23-related disorder as the primary diagnosis when Hmong patients present symptoms of lactic acidosis and hypoglycemia." (PMID 38086984, 2023).
metastatic disease (1 paper, 2006). "Furthermore, when gains and losses of MRPS23 and LSM3 occur, they may influence the gene expressions and possibly the development of metastatic disease." (PMID 17054779, 2006).
nasopharyngeal carcinoma (1 paper, 2026). A carcinoma arising from the nasopharyngeal epithelium. "Furthermore, to further validate the impact of MRPS7/MRPS23 knockdown on the stemness of nasopharyngeal carcinoma cells, we observed that knockdown of MRPS7 or MRPS23 markedly reduced the proportion of side population (SP) cells via flow cytometry." (PMID 41522354, 2026).
periodontitis (1 paper, 2022). An acute or chronic inflammatory process that affects the tissues that surround and support the teeth. "Interestingly, EZH1 and MRPS23 were newly identified, whereas previous studies have verified SIGLEC14 and SIGLEC5 as genetic risk factors for periodontitis." (PMID 36611863, 2022). "Finally, we identified two previously reported genes (SIGLEC5, SIGLEC14) and two novel genes (EZH1, MRPS23), proving that TWAS is a supplemental strategy for studying periodontitis’ etiology." (PMID 36611863, 2022).
triple-negative breast carcinoma (1 paper, 2026). An invasive breast carcinoma which is negative for expression of estrogen receptor (ER), progesterone receptor (PR), and human epidermal growth factor receptor 2 (HER2). "Besides, the long non-coding RNA HIF1A-AS2 facilitates tumor progression and confers paclitaxel resistance in triple-negative breast cancer through modulation of MRPS23 protein expression." (PMID 41522354, 2026).
tumor (11 papers, 2006 to 2026). "MRPS23 is an independent prognostic marker associated with tumor size, TNM stage, and overall survival (OS)." (PMID 39868366, 2024). "In hepatocellular carcinoma, increased MRPS23 expression is associated with larger, later stage tumours, and poor survival." (PMID 39354291, 2024). "However, the high expression of MRPS23 was associated with tumor proliferation and angiogenesis by changing the hypoxic state of tumor cells and increasing mitochondrial activity." (PMID 34359790, 2021). "To delineate the specific cell populations expressing MRPS7 and MRPS23 within the tumor microenvironment of NPC, we performed single-cell RNA sequencing (scRNA-seq) analysis using datasets NPC-GSE150430 and NPC-GSE162025 from the TISCH database." (PMID 41522354, 2026). "Strikingly, dual knockdown of MRPS7 and MRPS23 synergistically suppressed tumor growth by inhibiting β-catenin signaling, thereby attenuating EMT and cancer stemness." (PMID 41522354, 2026). "Knockdown of MRPS7 and MRPS23 not only suppresses tumor progression but also synergizes with cisplatin to enhance therapeutic efficacy." (PMID 41522354, 2026). "These divergent findings highlight the conserved oncogenic contributions of MRPS23 across various cancer types, while emphasizing its tissue-specific and mechanism-specific roles in tumor progression." (PMID 41522354, 2026). "In this study, we demonstrated that dual knockdown of mitochondrial ribosomal proteins MRPS7 and MRPS23 not only exerts intrinsic anti-tumor effects but also synergizes with cisplatin to enhance therapeutic outcomes." (PMID 41522354, 2026). "To delineate the role of MRPS7 and MRPS23 in promoting tumor progression and their potential functional interplay in NPC, we generated MRPS7 and MRPS23 single- and double-knockdown NPC cell lines in the Cne2 and C666 models." (PMID 41522354, 2026). "Strikingly, dual knockdown of MRPS7 and MRPS23 resulted in synergistic anti-tumor effects, mediated through the suppression of β-catenin signaling." (PMID 41522354, 2026). "Our findings revealed that the knockdown of MRPS7 and MRPS23 synergistically enhanced the anti-tumor efficacy of cisplatin in NPC." (PMID 41522354, 2026). "In summary, our study identifies MRPS7 and MRPS23 as pivotal oncogenic drivers that promote tumor growth, metastasis, and chemoresistance in NPC." (PMID 41522354, 2026). "Results showed that knockdown of MRPS7 or MRPS23 alone significantly reduced tumor size and weight, while combined knockdown exerted a more pronounced inhibitory effect on tumor growth." (PMID 41522354, 2026). "MRPS23 expression was significantly unregulated in HCC samples compared with adjacent non-tumor liver tissues." (PMID 34440674, 2021). "Patients with high MRPS23 expression had higher tumor-metastasis-node scores and significantly worse overall survival." (PMID 34440674, 2021). "When tumours were reclassified into four categories based on MRPS23 and HER2 status, the highest risk of death was found in the MRPS23+/HER2+ subtype." (PMID 31950385, 2020). "MRPS23 has previously been found to be amplified exclusively in highly proliferative luminal tumours." (PMID 31950385, 2020). "We found MRPS23 amplification (mean MRPS23 copy number ≥ 6 and/or MRPS23/chromosome 17 ratio ≥ 2) in 8% of primary tumours." (PMID 31950385, 2020). "Immunohistochemistry revealed that MRPS23 is strongly expressed in tumour tissues compared with adjacent non-tumour tissue." (PMID 29069745, 2017). "Knockdown of MRPS23 also inhibited the protein and mRNA expression of MRPS23 in shMRPS23-treated tumours, compared with Control and shCtrl groups (p < 0.05)." (PMID 29069745, 2017). "Consistent with a reversal of the EMT phenotype, down-regulation of MRPS23 limited the metastasis of the tumour into the surrounding lymph node, rendering the tumour smooth at its edges." (PMID 29069745, 2017). "Conversely, vimentin expression was repressed in MRPS23 knockdown tumours compared with shCtrl-infected samples." (PMID 29069745, 2017).
tumor (continued). "The colocalization of MRPS23 with LV depicted the inhibited expression of MRPS23 in shMRPS23-treated tumour." (PMID 29069745, 2017). "One group was associated with rapid proliferation, oxidative phosphorylation, invasiveness, and tumor size (MRPS23, MRPL11, CKS2, LSM3, TBX3, MSN) and another with hypoxia tolerance, anaerobic metabolism, and high lactate content (PDK2, KLF3)." (PMID 17054779, 2006). "Genetic silencing of MRPS7/MRPS23 decreased tumor burden by 54.13% versus controls." (PMID 41522354, 2026). "MRPS23 overexpression correlates with advanced tumor stage and reduced survival, although its direct role in metastatic dissemination remains unclear." (PMID 41522354, 2026). "We further explore the prognosis of MRPS23 in different tumor types." (PMID 38301044, 2024). "We continue to analyze the ROC curve values of MRPS23 in different tumor types." (PMID 38301044, 2024). "MRPS23 amplification was also identified in the lymph node metastases of two MRPS23-tumours." (PMID 31950385, 2020). "In the METABRIC dataset, Luminal B tumours had the highest level of MRPS23 gene expression." (PMID 31950385, 2020). "A total of 45 tumours (8%) were amplified (mean MRPS23 ≥ 6 and/or MRPS23/CEP17 ≥ 2)." (PMID 31950385, 2020). "MRPS23 copy number in primary tumours and lymph node metastases was assessed in TMAs." (PMID 31950385, 2020). "Interestingly, the MRPS23+ /HER2+ tumours had the poorest prognosis." (PMID 31950385, 2020). "Both tumor size and tumor-initiating capacity were significantly diminished in the MRPS7/MRPS23 knockdown groups." (PMID 41522354, 2026). "We further observed that MRPS7 and MRPS23 are significantly overexpressed in NPC, and their suppression potentiates cisplatin's efficacy in inhibiting subcutaneous tumor growth and pulmonary metastasis in NPC xenograft models." (PMID 41522354, 2026). "To further evaluate the clinical relevance of MRPS7 and MRPS23 in NPC, we performed IHC staining on tumor specimens from 41 patients who had received cisplatin (DDP)-based therapy." (PMID 41522354, 2026). "In the meanwhile, we observed that both MRPS7 and MRPS23 were significantly overexpressed in NPC, further supporting their potential roles in promoting tumor progression across relevant malignancies." (PMID 41522354, 2026). "Using subcutaneous tumor xenografts, knockdown of MRPS7 and MRPS23 dramatically potentiated cisplatin efficacy, leading to substantial decreases in both tumor volume and mass in cisplatin-administered murine models." (PMID 41522354, 2026). "Collectively, these findings demonstrate that MRPS7 and MRPS23 function as tumor promoters in NPC, with combined knockdown exhibiting synergistic inhibition of tumor progression and metastasis in NPC." (PMID 41522354, 2026). "Some researchers have found that high MRPS23 levels can predict a poor outcome in HCC, and this protein plays an important role in tumor progression." (PMID 38093387, 2023). "Thus, the role of MRPS23 in ACC metastasis might be different from that in tumor proliferation." (PMID 34359790, 2021). "When MRPS23 and CEP17 copy number alterations were present, a homogenous pattern was seen, with alterations in the majority of tumour cells." (PMID 31950385, 2020). "There were no significant changes in MRPS23 copy number status in the lymph node metastases compared to the corresponding primary tumours." (PMID 31950385, 2020). "Of the MRPS23 amplified tumours, 66% had high Ki67 (≥ 15%), compared to 39% of the non-amplified tumours." (PMID 31950385, 2020). "To gain additional mechanistic insight into the role of MRPS23 in the metastasis cascade, we focus on the epithelial marker E-cadherin and mesenchymal marker vimentin, which play a major role in the EMT process that contributes to tumour progression." (PMID 29069745, 2017).
tumor (continued). "Here, our study revealed that knockdown expression of MRPS7 and MRPS23 exhibited an anti-tumor effect and have a synergistic effect with cisplatin, further investigation into the regulatory mechanisms revealed that USP10 acts as a key regulator of MRPS7 and MRPS23 expression." (PMID 41522354, 2026). "A significant upregulation of MRPS7, MRPS23, and USP10 was observed in tumor tissues relative to matched adjacent non-tumor tissues." (PMID 41522354, 2026). "Three different phenotypes were seen, tumours without copy number alterations; tumours with MRPS23 and CEP17 copy number increase and tumours with MRPS23 copy number increase only." (PMID 31950385, 2020). "Of the MRPS23 amplified tumours, 56% were grade III, compared to 31% of the non-amplified tumours." (PMID 31950385, 2020). "Given that knockdown of USP10 reduced the expression of MRPS7 and MRPS23, and considering the lack of potent antagonists targeting MRPS7 and MRPS23 directly, we investigated spautin-1, a well-characterized USP10 inhibitor with demonstrated anti-tumor effects, as a potential therapeutic agent." (PMID 41522354, 2026).